RNU6-417P (RNA, U6 small nuclear 417, pseudogene)
Gene: Small nuclear RNA gene on chromosome 7 (63,011,463 to 63,011,569, reverse strand). Ensembl gene ENSG00000207443.
Homologues: Orthologues: chimpanzee U6 (98% identical). Paralogues in human: RNU6-15P (90% identical), RNU6-20P (90% identical), RNU6-211P (90% identical), RNU6-1145P (89% identical), RNU6-154P (89% identical), RNU6-16P (89% identical), RNU6-25P (89% identical), RNU6-41P (89% identical), RNU6-820P (89% identical), RNU6-1 (88% identical), RNU6-1152P (88% identical), RNU6-1263P (88% identical), and 1288 more.